CRELD2 (CRELD disulfide isomerase 2)
Diseases named in the same sentence as CRELD2 in open-access papers (continued):
Sharing a sentence is not in itself a finding about the gene and the disease.
cancer (7 papers, 2021 to 2025). A tumor composed of atypical neoplastic, often pleomorphic cells that invade other tissues. "The cysteine-rich epidermal growth factor ligand domain 2 protein (CRELD2) is associated with pathways that regulate epithelial-to-mesenchymal transition, a critical process driving cancer metastasis." (PMID 39869369, 2025). "CRELD2 has been implicated in various physiological and pathological processes, including hepatic metabolic homeostasis, cartilage and bone metabolism, and cancer progression." (PMID 40821803, 2025). "Their results showed that CRELD2 is a paracrine factor that underlines PERK-mediated cancer-associated fibroblast education downstream of Rho-associated kinase (ROCK) via an analysis of tumors from patients and mice." (PMID 36936176, 2023). "recently established a causal link between CRELD2 and cancer." (PMID 36936176, 2023). "As a novel ER stress-responsive gene, Creld2 is highly correlated with cancer development, although the detailed underlying pathophysiology remains unclear." (PMID 36936176, 2023). "Recent studies suggest that CRELD2 is associated with cartilage/bone metabolism homeostasis and pathological conditions involving ER stress such as chronic liver diseases, cardiovascular diseases, kidney diseases, and cancer." (PMID 36936176, 2023). "Moreover, CRELD2 is associated with various diseases and has crucial roles in various physiological and pathological processes, including liver metabolism homeostasis, cartilage and bone metabolism, and cancer progression and survival, as well as potential role as a biomarker for kidney diseases." (PMID 36936176, 2023). "However, animal and cell models suggest that CRELD2 is a novel ER stress-responsive protein that might be implicated in ER homeostasis and ER stress-related diseases, including chronic liver diseases, CVDs, kidney diseases, and cancer." (PMID 36936176, 2023). "Additionally, CRELD2 has been implicated in pathways regulating epithelial-to-mesenchymal transition (EMT), a key process driving cancer metastasis." (PMID 39869369, 2025). "Our study provides a plausible explanation for the roles of CRELD2 and APMAP in cancer cells undergoing ER stress." (PMID 40821803, 2025). "Margin skin, which had been assessed histo‐pathologically to contain no cancer cells, exhibited relatively low levels of CRELD2, and hyperplastic regions exhibited higher levels." (PMID 38979935, 2024).
kidney diseases (7 papers, 2018 to 2025). "Urinary CRELD2 can be used to distinguish between controls and patients with early kidney disease." (PMID 36936176, 2023).
skeletal diseases (3 papers, 2013 to 2024). "This study demonstrates for the first time the genotype-specific upregulation and secretion of Armet and Creld2 in various cell and mouse models of genetic skeletal diseases." (PMID 23956175, 2013). "In mouse models of genetic skeletal diseases in which misfolded structural proteins trigger ER stress and UPR signaling, CRELD2 has been proposed to function as a protein disulfide isomerase, acting in concert with other protein disulfide isomerases and chaperones inside the ER29." (PMID 39196188, 2024).
connective tissues diseases (1 paper, 2013). "The role of ER stress and UPR specialization in these connective tissues diseases, and in particular whether ARMET and Creld2 are up-regulated, warrants further investigation in order to delineate a range of different phenotypes that may share a common disease trigger." (PMID 23956175, 2013).
genetic diseases (1 paper, 2013). "Despite these recent descriptions, the precise roles of Creld2 and Armet remain poorly understood in human biology and genetic diseases." (PMID 23956175, 2013).
skeletal dysplasia (1 paper, 2022). Any Mendelian diseases that affects growth and development of the skeleton. "CRELD2 is an ER-stress regulated gene that has been implicated in the pathogenesis of skeletal dysplasias and has been shown to play an important role in the differentiation of chondrocytes and osteoblasts." (PMID 35974042, 2022).
CRELD2 also shares sentences with these, for which no sentence is quoted: diabetes (3 papers); acute myocardial infarction (1); Autosomal Dominant Tubulointerstitial Kidney Disease (1); cardiovascular diseases (1); cutaneous squamous cell carcinoma (1); esophageal cancer (1); esophageal squamous cell carcinoma (1); Hepatic steatosis (1); ischemia (1); kidney (1); kidney cancer (1); lung squamous cell carcinomas (1); neurodegenerative disease (1); neuropathy (1); osteogenesis imperfecta (1); osteoporosis (1); overnutrition (1); Wolfram syndrome (1).